OR9A1P (olfactory receptor family 9 subfamily A member 1 pseudogene)
Description:
Odorant receptor.
Synonyms: OR9A1; HTPCRX06; HSHTPCRX06; OR9A5P
Gene: Protein-coding gene on chromosome 7 (141,887,148 to 141,888,092, forward strand). Ensembl gene ENSG00000237621.
Subcellular location: Cell membrane
Homologues: Orthologues: chimpanzee OR9A1P (93% identical), pig OR9A1P (79% identical), mouse Or9a7 (78% identical). Paralogues in human: OR9A4 (73% identical), OR9A2 (72% identical), OR11G2 (39% identical), OR11H6 (38% identical), OR11H4 (36% identical), OR11H7 (35% identical), OR11H1 (34% identical), OR11H12 (34% identical), OR11H2 (34% identical), OR10X1 (34% identical), OR11A1 (33% identical), OR9G1 (32% identical), and 21 more.